ZFAT-AS1 (ZFAT antisense RNA 1)
Synonyms: SAS-ZFAT; NCRNA00070; ZFAT-AS; ZFATAS
Gene: Long non-coding RNA gene on chromosome 8 (134,598,071 to 134,600,689, forward strand). Ensembl gene ENSG00000248492.
Gene Ontology:
Biological process: negative regulation of gene expression